MMP9 (matrix metallopeptidase 9)
Diseases named in the same sentence as MMP9 in open-access papers (continued):
Sharing a sentence is not in itself a finding about the gene and the disease.
Stroke (continued). "Matrix metalloproteinase-9 (MMP-9) are inflammatory mediators of the endoproteinase family, and their polymorphism and methylation are associated with the development of atherosclerosis and stroke." (PMID 35002488, 2021). "One of the key factors contributing to increased BBB permeability after stroke is MMP-9." (PMID 33807314, 2021). "Overall, current evidence suggests that MMP-9-mediated BBB dysfunction following stroke may constitute an early pathological mechanism that initiates the neurodegenerative cascades leading to cognitive deficits over time." (PMID 34566627, 2021). "MMP9 and other plasma inflammatory factors are modified in the acute stages of stroke inflammation, which suggests their involvement in the development and progression of stroke pathology." (PMID 33346402, 2021). "To further rule out the potentially compensatory effects of COX-2 gene deficiency in mice following stroke, we also investigated the effects of CAY10404, a highly selective COX-2 inhibitor, on BBB damage, hemorrhagic transformation, and MMP-9 activity in wild-type mice subjected to focal ischemia." (PMID 32973660, 2020). "Similarly, stroke resulted in a dramatic increase in MMP-9 activity in the ipsilateral cortex of COX-2+/+ mice, and this increase was significantly attenuated in COX-2−/− mice." (PMID 32973660, 2020). "It was suggested that MMP-9 was also involved in cerebral damage following stroke events." (PMID 32466129, 2020). "Interestingly, we observed a joint effect of serum TIMP‐1 and MMP‐9 on post‐stroke cognitive impairment." (PMID 32431079, 2020). "Apart from these, there is also some evidence suggesting positive role of MMP-9 in stroke recovery." (PMID 31701356, 2020). "However, Ly6G+ neutrophils demonstrated the highest production level of MMP-9 in the ischemic brain at 72 hours (vs. stroke microglia p<0.01, vs. Ly6Chi p<0.001, vs. Ly6Clo p<0.05)." (PMID 32191628, 2020). "In line with the BBB permeability data, stroke-induced loss of tight junction proteins including ZO-1 and occludin was significantly attenuated by CAY10404 treatment in the ischemic brain, which were associated with significant reduction of MMP-9 activity." (PMID 32973660, 2020). "Moreover, circulating TIMP‐1 and MMP‐9 had been reported to be increased in stroke, multiple sclerosis and other neurological diseases." (PMID 32431079, 2020). "This level corresponds to doubled levels of MMP-9 in blood following a stroke." (PMID 32843630, 2020). "Interestingly, despite the lack of CD147 up-regulation on resident microglia, there was a significant increase in the target of CD147, MMP-9, in microglia from stroke mice compared to sham (p=0.001, n=7)." (PMID 32191628, 2020). "Another molecule related to BBB dysfunction is MMP9, which is up-regulated after stroke and TBI." (PMID 32878052, 2020). "Interestingly, BR therapy remarkably reduced the levels of MMP-9 in the plasma of recipient stroke mice at both early and late time points." (PMID 32843630, 2020). "The data clearly demonstrated that MMP-9 diminished the therapeutic effects of BR in stroke and suggested that a reduced level of MMP-9 could be one of the important mechanisms used by the BR therapy in stroke." (PMID 32843630, 2020). "MMP-9 mediates BBB permeability by degrading tight junction proteins in the acute stage of stroke." (PMID 33510620, 2020). "In addition, flow cytometry and enzyme-linked immunosorbent assay (ELISA) have demonstrated substantially reduced neutrophils and decreased levels of MMP-9 in the blood and brains of stroke mice, which received whole blood obtained from naive donor mice." (PMID 32843630, 2020). "Given that BR therapy robustly reduced neutrophil counts in the peripheral blood and significantly decreased the infiltration of neutrophils and macrophages/monocytes in ischemic hemispheres, it is important to further investigate how MMP-9 is involved in BR-treated stroke." (PMID 32843630, 2020).
Stroke (continued). "It is not clear how baicalin reduces the expression of MMP-9, but it is known that inhibition of NFκB may reduce the transcription of the MMP-9 gene in stroke models, decreasing the expression of MMP-9." (PMID 33261005, 2020). "Interestingly, MMP-9-treated blood significantly exacerbated stroke infarction and worsened neurological deficits, whereas vehicle-treated blood profoundly protected stroke outcomes following 60 min tMCAO and 22 h reperfusion." (PMID 32843630, 2020). "First, although the limited sample size and the monocentric design may be considered as a limitation, its major strength lies in sequential assessment of MMP-9 coupled with MRI data within a homogeneous cohort of stroke patients with LVO in the context of MT." (PMID 32582006, 2020). "Our recent study found that serum MMP‐9 could be a biomarker for predicting post‐stroke cognitive impairment." (PMID 32431079, 2020). "MMP‐9 inhibitors can decrease the BBB destruction in the experimental stroke model." (PMID 31012282, 2019). "Indeed, higher serum levels of MMP-9 at stroke onset have been shown to predict poor outcome in the acute period." (PMID 29752550, 2018). "MMP-9 may be responsible for this ECM reorganization as a number of studies have demonstrated increased MMP-9 levels following CNS injury and stroke in humans as well as animal models." (PMID 30123106, 2018). "Some clinical studies have suggested that the levels of circulating MMP-9 are significantly correlated to disease severity and infarct volume in the hyperacute phase, as well as late hemorrhagic infarction incidence between 5 and 7 days after stroke onset." (PMID 30131754, 2018). "This is relevant because MMP-9-induced BBB opening is detrimental in the acute phase of stroke." (PMID 29527151, 2018). "In fact, studies in stroke victims have identified a strong association between MMP9 and diffusion MR measures of the apparent diffusion coefficient (ADC), an association which was confirmed by gene knockdown of MMP9 activity in mouse studies." (PMID 30517112, 2018). "Moreover, it has been proposed that detrimental effects of tPA beyond the 3 h of stroke onset are derived from tPA’s ability to activate MMP-9." (PMID 29724240, 2018). "In addition to regulating post stroke inflammatory responses, MMP9 also plays an important role in post stroke angiogenesis and BBB disruption." (PMID 29896433, 2018). "Furthermore, clinical studies of stroke have found a correlation between MMP-9 levels in the blood and the rate of haemorrhagic transformation." (PMID 28779350, 2018). "MMP-9 expression and hemorrhagic transformation after stroke increased with age." (PMID 29752550, 2018). "Although inhibition or knockout of MMP-9 attenuates early degradation of the BBB in MCAO models, it is ineffective in preventing later opening of the BBB at 48 h after IS, and MMP-9 is thought to be beneficial in later stroke recovery, especially in promoting angiogenesis and neurogenesis." (PMID 30572925, 2018). "The relationship of MMP-9 with stroke severity and cognitive function in this study may be due to the relatively large number of stroke patients with the Met allele." (PMID 30322026, 2018). "Similarly, MMP-9 production was twofold higher in aged neutrophils after stroke compared to monocytes." (PMID 29752550, 2018). "This self-perpetuating loop of MMP-9 expression after tPA administration may explain why higher levels of MMP-9 expression predict more severe intracranial hemorrhage with thrombolytic treatment in human stroke." (PMID 29963617, 2018). "In order to discern if the increased activity of MMP-9 and tPA that we see in the stroke EE group was due to changes in expression of respective ECM proteases, mRNA levels of Mmp9, as well as Adamts4, Tpa, and their inhibitors (respectively, Timp1, Timp3, and Neuroserpin) were studied by RT-qPCR." (PMID 28290150, 2018).
Stroke (continued). "However, elevated levels of MMP-9 on days 7–14 post-stroke played a beneficial role in angiogenesis and brain recovery." (PMID 30237808, 2018). "Elevated MMP-9 levels can be used as predictor of poor prognosis and stroke-related death." (PMID 30245755, 2018). "Circulating MMP9 has also been shown to predict clinical events such as stroke and fatal CVD." (PMID 28319050, 2017). "In patients with stroke, a significant decrease in serum miR-124 expression was found within 24 hours post stroke, and decreased miR-124 correlated with increased infarct volume and neuroinflammatory factor matrix metalloproteinase 9 (MMP9) expression." (PMID 29221142, 2017). "MMP9 is a neuroinflammatory factor that is elevated after stroke, and has been associated with WM injury, BBB disruption, worse neurological deficits and increased infarct volume after stroke." (PMID 29221142, 2017). "A greater MMP-9 activity was found in diabetic rats following stroke." (PMID 28115020, 2017). "DM-stroke significantly increases MMP9 activity compared to non-DM stroke, and MMP9 has been specifically implicated in the disruption of the BBB and neuronal cell death following cerebral ischemia." (PMID 29221142, 2017). "As upregulation of MMP9is associated with activation of MEK/ERK in neurological diseases such asischemic stroke, we examined whether Erk1/2 also elevated Mmp9 infn40a mutants." (PMID 28153846, 2017). "Additionally, MMP‐9 is important in vascular remodeling after stroke and inhibiting MMP‐9 1 week after stroke increases infarct size and worsens outcomes." (PMID 28523230, 2017). "Furthermore, MMP-9 has been shown to be elevated in the serum of stroke patients and is correlated with a worsened outcome." (PMID 26973468, 2016). "Increased MMP-9 levels have been well documented following both experimental and clinical stroke." (PMID 26973468, 2016). "These inflammatory cells are good candidates to be the main source of MMP-9 post-stroke in the setting of tPA treatment, and may be responsible, at least in part, for tPA-induced hemorrhage." (PMID 26973468, 2016). "The aim of the present review is to examine the relationship between neutrophils, MMP-9 and tPA following ischemic stroke to elucidate which cells are responsible for the increases in MMP-9 and resultant barrier changes and hemorrhage observed following stroke." (PMID 26973468, 2016). "MMP-2, MMP-3, MMP-9, MMP-13, and MT1-MMP have all been identified in neuronal nuclei and gelatinases (MMP-2 and MMP-9) and MMP-3 have been implicated in the progression of infarct volume and neuronal death in animal models of stroke and ischemic stroke patients." (PMID 26925194, 2016). "This elevation in MMP-9 was determined to be a marker of stroke for patients arriving within 12 h of stroke onset, with MMP-9 levels even proposed as a marker that could predict the probability of stroke." (PMID 26973468, 2016). "This suggests that neutrophils may be responsible for the early increases in MMP-9 observed in plasma following stroke." (PMID 26973468, 2016). "Specifically, the MMP9/ Timp1 was elevated on the seventh day of stroke, which might provide a biomarker of prognosis." (PMID 27213359, 2016). "However, just as MMP-9 levels are elevated following stroke, the expression of TIMP-1, the endogenous inhibitor of MMP-9, has also been shown to be dysregulated following stroke." (PMID 26973468, 2016). "Although it is generally accepted that MMP-9 is increased following stroke, there is debate as to which cells are responsible, whether it be resident brain cells, cells of the vasculature or circulating immune cells, such as neutrophils." (PMID 26973468, 2016). "Such tPA-activation of MMP-9 may further amplify the MMP-9 response to stroke and involvement in injury pathways." (PMID 26973468, 2016). "Furthermore, the gelatinase MMP-9 lowered by VSL#3 indicated its potential association with lowered risk of thrombotic events, for example stroke and ischemia." (PMID 27576894, 2016).
Stroke (continued). "Furthermore, in anti-stroke target analysis, we found MMP9 was up-regulated in the total and all subgroups." (PMID 27672514, 2016). "Concerning therapeutic strategies in stroke, a recent review of the literature discussed the current status of neuroprotection and extension of thrombolytic window by directly or indirectly inhibiting MMP-9 activity." (PMID 26074872, 2015). "MMP-9 has been extensively studied for its involvement in BBB disruption after stroke." (PMID 25897666, 2015). "With these observations and the established role of MMP-9 in neurological injury in stroke, we hypothesized that ac-PGP could be produced in brain during ischemia/reperfusion injury." (PMID 26588897, 2015). "In experimental stroke models, early statin administration enhances thrombolysis, augments antithrombotic responses, increases cerebral blood flow, and decreases matrix metalloproteinase-9 (MMP-9) levels." (PMID 26224069, 2015). "Thus, composite measures including both CHD events and stroke should be used with caution when evaluating MMP-9 as a predictive marker." (PMID 26389803, 2015). "In conclusion, our findings suggest that MMP-9 C(-1562)T polymorphism is significantly associated with risk of stroke in patients with and without T2DM." (PMID 26330106, 2015). "MMP9 as a matrix metalloproteinase could be involved in neuroblast cells migration and hence helped neurogenesis in stroke recovery." (PMID 26030758, 2015). "In conclusion, chronic hyperglycemia aggravated hemorrhagic transformation after stroke through mitochondrial dysfunction and morphological alteration, partially via MMP-9 activation, leading to caspase-dependent apoptosis of endothelial cells of diabetic mice." (PMID 25133692, 2014). "Matrix metalloproteinase-9 (MMP-9) is a serine protease that becomes activated in case of ischemic brain injury and has been shown to be a key mediator of blood–brain barrier breakdown in experimental stroke." (PMID 24499647, 2013). "All these data proposes MMP-9 as a key protease in post-stroke angiogenesis mediated by EPCs." (PMID 23945132, 2013). "Importantly, minocycline can lower plasma MMP-9 levels, even at 72 h after stroke, and improve neurological outcomes in acute ischemic stroke patients treated with tPA." (PMID 23565108, 2013). "Although MMP-9 is detectable in the brain after stroke, its cellular source remains controversial." (PMID 23565108, 2013). "Alternative thrombolytic agents or therapeutic inhibition of MMP-9 may increase the safety profile of acute stroke thrombolysis." (PMID 23565108, 2013). "Amongst MMPs, gelatinases (MMP-2, MMP-9) activity and expression are up-regulated after stroke." (PMID 23940734, 2013). "For example, MMP-9 expression is elevated shortly after ischemia and stroke." (PMID 22567285, 2012). "Hypothermia attenuated both the optical increase in intensity after MMPSense750 and the increase in MMP-9 protein expression supporting the proof of concept that NIRF imaging using MMPSense can be used to assess potential therapeutic strategies for stroke treatment." (PMID 22742423, 2012). "Moreover, a possible involvement of ADMA in post-ischemic recovery is supported by the fact that ADMA was inversely correlated with MMP-9 at 12 hours after stroke onset in our study." (PMID 23158556, 2012). "In general higher MMP-9 levels are shown to correlate significantly with larger infarct volume, severity of stroke, reduced survival of neurons and worse functional outcome, and therefore, seem an appropriate target for a robust neuroprotectant such as hypothermia." (PMID 22742423, 2012). "We demonstrated MMP-9 activation and neurovasculature impairment in stroke, and showed the ability of SB-3CT to inhibit MMP-9 activity in vivo, which resulted in maintenance of laminin, antagonism of pericyte contraction and loss, and preservation of laminin-positive pericytes and endothelial cells." (PMID 22587708, 2012).
Stroke (continued). "In time dependent studies we detected the maximum MMP-9 level in the brain at 6 hours post stroke." (PMID 22177314, 2011). "In our stroke cohort, day 1 MMP-9 and MMP-9/TIMP-1 ratio correlated with acute DWI lesion volumes." (PMID 21871109, 2011). "Higher TIMP-1 levels were mainly related to higher risk of stroke and cardiovascular mortality, and higher MMP-9 levels mainly to risk of non-cardiovascular mortality." (PMID 21283828, 2011). "No SNP or haplotype in the MMP-9 gene was associated with stroke outcome at three months in the ischemic subset." (PMID 20222942, 2010). "Haplotype tagging single nucleotide polymorphisms (SNPs) in the MMP-2 (N = 21) and MMP-9 (N = 4) genes were genotyped and tested for association with stroke outcome, adjusting for significant non-genetic clinical variables." (PMID 20222942, 2010). "This suggested that MMP-9 may play an active role in early vasogenic edema development after stroke." (PMID 20514206, 2009). "MMP-9 peaks at 48 hours while MMP-2 peaks at 5 days post stroke." (PMID 19497125, 2009). "However, when considering the individual outcomes of TIA or stroke in another study, neither endpoint presented an association with MMP-9 levels." (PMID 40364266, 2025). "And MMPs, especially MMP-9, are involved in the pathological processes of neuroinflammation, epilepsy, schizophrenia, autism spectrum disorder, multiple sclerosis, cerebral aneurysm, stroke, subarachnoid hemorrhage, Alzheimer’s disease, and Parkinson’s disease." (PMID 38275397, 2024). "Additionally, the higher levels of VEGF, MMP9, infarct volume, and edema in older pregnant mice further support the idea that pregnancy at an older age may have detrimental effects on stroke outcomes." (PMID 39309404, 2024). "Indeed, our research was specifically conducted during the subacute phase of stroke; as such, our data may suggest that MMP-9 could play a role in promoting neuroplasticity during this stage." (PMID 38891934, 2024). "Moreover, high levels of MMP-9 have been found between 7 and 14 days post-stroke." (PMID 39599732, 2024). "Furthermore, female MMP-3 KO stroke brains showed decreased expression of apoptosis signaling genes Casp6, Tnfrsf1b, Tnfrsf1a, and Tnf, and downregulated expression of matrix metalloprotease genes Mmp14, Mmp9, and Mmp11." (PMID 39000490, 2024). "Older patients who experienced stroke (>71 years) had more pronounced hyperemia and hemorrhage than younger patients, and neutrophil infiltration was found in the brain parenchyma (areas of hemorrhage and congestion), thus reflecting increased MMP-9 levels and BBB disruption." (PMID 37728582, 2024). "Furthermore, the study provides valuable insights into the role of MMP-9 in post-stroke epileptogenesis, suggesting that its absence may have a protective effect, while its overexpression may potentiate seizure susceptibility." (PMID 38255970, 2024). "However, inhibition of MMP-2 and MMP-9 confers neuroprotection in stroke." (PMID 39654616, 2024). "However, stratification by ethnicity showed a significant association between MMP-9-1562C/T polymorphism and increased stroke risk only among Asians, but not among Europeans (TT + CT vs. CC)." (PMID 37206663, 2023). "Furthermore, MMP-9 levels appear to have predictive value for hemorrhagic transformation, with the highest level of MMP-9 recorded six hours after stroke onset, and an increased level of MMP-9 being associated with infarct exacerbation and hemorrhage conversion." (PMID 37371326, 2023). "Our present findings suggest that the combined protein and mRNA expression of MMP-9 may be a useful biomarker for cognitive improvement in post-stroke patients, assuming an increase of three points on the MMSE scale, and that this test offers 87% sensitivity and 71% specificity." (PMID 37371326, 2023). "There are several mechanisms of how MMP-9 may affect the environment in strokes." (PMID 37206663, 2023).